CD38 (CD38 molecule)
Diseases named in the same sentence as CD38 in open-access papers (continued):
Sharing a sentence is not in itself a finding about the gene and the disease.
multiple myeloma (continued). "However, the effects of ISA are strongly related to CD38 expression (which could be a drawback in the AL amyloidosis setting as this condition is characterized by a small burden of abnormal PCs) and both ISA and MOR202 seem to require IMiD co-operation to achieve an optimal effect." (PMID 32531894, 2020). "The role of CD38 in CLL and multiple myeloma has been reviewed previously and is highlighted by other articles in this issue." (PMID 31878283, 2019). "Immunophenotyping data indicate that the combination of CD38 and CD138, another known marker of fully differentiated plasma cells, is a validated strategy to identify CD45+ myeloma and separate CD20+ myeloma from B-cell lymphoma." (PMID 31636635, 2019). "The aim of this study was to evaluate the relation between the rate of fluorine-18 (18F) fludeoxyglucose (FDG) uptake and CD38 and CD138 expression in myeloma cells in bone marrow and other clinical parameters in patients with multiple myeloma (MM)." (PMID 29806594, 2018). "While these data suggest that CD38 is an attractive therapeutic target in ENKTL, most of the research on daratumumab has been in multiple myeloma and ENKTL-specific mechanisms of action and resistance will have to be investigated." (PMID 29966370, 2018). "The approval of the first two monoclonal antibodies targeting CD38 (daratumumab) and SLAMF7 (elotuzumab) in late 2015 for treating relapsed and refractory multiple myeloma (RRMM) was a critical advance for immunotherapies for multiple myeloma (MM)." (PMID 30147690, 2018). "Daudi cells have over 250,000 molecules of CD38 per cell on their surface while KG-1 cells have 85,000 per cell and CD34+ mobilized cells from myeloma patients have less than 10,000 per cell." (PMID 30356940, 2018). "Multiple myeloma cells express other cell-surface tumor antigens that can be targeted, such as CS1, CD38, and CD33." (PMID 30208593, 2018). "The correlations between the average SUVmean of bone marrow and CD38- and CD138-expressing myeloma cells and other parameters were analyzed by Spearman’s correlation test." (PMID 29806594, 2018). "Trials with daratumumab and other anti-CD38 antibodies are ongoing for upfront treatment of symptomatic (e.g., NCT03012880 and NCT02541383) and asymptomatic/smoldering myeloma (e.g., NCT02316106) as well as AL-amyloidosis." (PMID 30079070, 2018). "As a TAA, CD38 has been used as a target via monoclonal antibody treatment (Daratumumab), which was approved by the FDA in 2015 for patients with multiple myeloma." (PMID 30031396, 2018). "Perhaps, the situation in myeloma is similar: high levels of CD38 may be beneficial for myeloma cell survival and conversely the low levels of expression imposed by treatment with daratumumab may render the myeloma cells more vulnerable to other anti-myeloma treatments." (PMID 29915586, 2018). "Using GEP, we found CD38 expressed in all 1,371 malignant plasma cell samples derived from symptomatic, relapsed, asymptomatic, MGUS-, and AL-amyloidosis patients." (PMID 30079070, 2018). "First, significantly increased levels of CD38 were shown on the cell membrane of Tregs (CD4+CD25highFoxp3+) and myeloma cells when compared with conventional T (Tcon, CD4+CD25−) cells containing the majority of effector T cells." (PMID 31548533, 2017). "The expression pattern of CD38 was evaluated by flow cytometry on primary CD138+ purified from 16 MM patients, human myeloma cell lines (HMCLs) and microenvironment cell lines." (PMID 28915615, 2017). "Despite early disappointments, monoclonal antibodies targeting CD38 (daratumumab) and signaling lymphocytic activation molecule F7 (SLAMF7) (elotuzumab) have become available for patients with multiple myeloma in the same year." (PMID 31548533, 2017). "In a preclinical study, isatuximab induced cell death in myeloma cell lines by ADCC, CDC, and ADCP, as well as the induction of tumor cell death in a CD38-dependent manner." (PMID 31548533, 2017).
multiple myeloma (continued). "Like other multiple myeloma antigens, i.e., SLAMF7, CD138, CD38, soluble BCMA was detected in the elevated levels in the serum samples of multiple myeloma when compared with normal donors." (PMID 31548533, 2017). "A second anti-CD38 mAb, SAR650984 (known clinically as isatuximab), also showed potent anti-myeloma activity in vitro and in vivo." (PMID 27618026, 2016). "We recently reported that T cells with anti-CD38-CAR efficiently eliminated B-cell lymphoma cells and myeloma cells expressing CD38 in vitro and in vivo." (PMID 28090317, 2016). "The expression status of CD13, CD19, CD20, CD33, CD38, CD56, and CD117 was analyzed on myeloma cells from 55 newly diagnosed patients, including 36 men (65%), of median age 61 years (range: 38–78)." (PMID 24991573, 2014). "Most of plasma cell myelomas are CD19-, CD45-/dim positive, CD38+++ and CD138+, while CD19 positivity is seen in lymphomas including the marginal zone lymphoma or lymphoplasmacytic lymphoma." (PMID 16901345, 2006). "Unlike ATRA, Panobinostat upregulates CD38 expression on myeloma and on lymphoma cells, while sparing normal cells." (PMID 40013150, 2025). "The aim of our study was to develop CD38-specific nanobody-based BARs specific for three distinct, non-overlapping epitopes on CD38 and to evaluate their potential to induce lysis of myeloma cells in vitro and ex vivo." (PMID 41254160, 2025). "Most CD38 inhibitors are antibodies; for example, Darzalex (daratumumab) is used primarily to treat patients with multiple myeloma; however, CD38 antibodies do not inhibit intracellular CD38." (PMID 40153575, 2025). "Fluorescence overlap (yellow) was observed only in PKH26‐stained RPMI8226 and U266 (red) myeloma cells, but not in CD38‐negative MSCs or K562 leukaemia cells, demonstrating that the synthesised CD38pep specifically bound to CD38‐positive myeloma cells." (PMID 40317915, 2025). "It targets CD38-expressing myeloma cells via immune-mediated mechanisms (CDC, ADCC, ADCP) and direct apoptosis, while also influencing CD38-positive immune cells such as Bregs, myeloid-derived suppressor cells, and a recently identified immunosuppressive CD38+ Treg subset." (PMID 41007627, 2025). "Tumors that express CD38, such as PBL and myelomas, are specifically targeted by daratumumab, which exerts its therapeutic effects through antibody-dependent cellular cytotoxicity, antibody-dependent cellular phagocytosis, complement-mediated lysis, and direct apoptosis." (PMID 39897241, 2025). "In preclinical studies, ISB 2001 was able to robustly kill myeloma cells even if one of the antigens (BCMA or CD38) was absent." (PMID 40702106, 2025). "An immunomodulatory agent-based quadruplet including anti-CD38 therapy has not been investigated as a first-line treatment in AL amyloidosis." (PMID 39980430, 2025). "In a mouse xenograft model harboring NCI-H929 multiple myeloma cells, our BsAbs inhibited tumor growth more potently than the monospecific anti-CD47 ligand trap, anti-CD38 (isatuximab) or combination of isatuximab and an anti-CD47 ligand trap at the same molecular dose per body weight." (PMID 38983860, 2024). "First, we examined CD38 target expression by dividing the mean fluorescence intensity (MFI) of CD38 on CD38+CD138+ multiple myeloma cells by that of CD38−CD138− non-MM cells." (PMID 38421887, 2024). "We found that primary multiple myeloma cells sensitive to SAR442257 had a CD38 MFI 6-fold brighter than the surrounding non-MM cells in culture, with the exception of two samples, HTB-1410 and HTB-1802." (PMID 38421887, 2024). "In fact our results indicate that ex vivo exposure of primary myeloma cells to tinostamustine does not generally augment the levels of CD38 but is able to increase the expression of MICA and MICB." (PMID 38731936, 2024). "First‐line treatment of multiple myeloma, a prevalent blood cancer lacking a cure, using anti‐CD38 daratumumab antibody and lenalidomide is often inadequate due to relapse and severe side effects." (PMID 38477561, 2024).
multiple myeloma (continued). "This is consistent with our finding that of the 29/34 patient aspirates responding to SAR442257, and the most promising biomarker of response was high CD38 expression on multiple myeloma cells relative to surrounding non-MM cells." (PMID 38421887, 2024). "This allows the CAR to recognize extracellular antigens, which, in the case of multiple myeloma, is mainly the B-cell maturation antigen (BCMA); however, multiple myeloma cells express on their surfaces a multitude of other antigens (GPCR5, CD38, FcRH5, etc.)that can be targeted by specific CARs." (PMID 39175472, 2024). "Similarly, CD38 knockout dual CAR-NK cells targeting BCMA antigen were able to prevent trogocytosis and maintained high cytotoxicity against multiple myeloma cells." (PMID 38726000, 2024). "Thereafter, daratumumab, a human monoclonal antibody directed against CD38 expressed on myeloma cells was initiated, which led to a negative immunofixation study after two cycles accompanied by a reduction in protein excretion in the urine." (PMID 38681439, 2024). "CD38 as a targeted therapy (daratumumab) has been approved for multiple myeloma, but it has also been suggested for SADs, particularly SLE, where plasma cells do not express CD20, leading to rituximab resistance; however, they highly express the CD38." (PMID 38726007, 2024). "Despite this, the anti-CD38 CAR-T cells effectively target myeloma cells, supporting previous findings that CD38 is not essential for T cell functionality." (PMID 39468695, 2024). "Targeting CD38 is not new in the multiple myeloma field, as CD38 mAbs Dara and Isa are commonly given in earlier lines of therapy." (PMID 38421887, 2024). "While TNFRSF17 (BCMA) was highly specific for myeloma samples, other immunotherapy targets such as CD38, CD138 (SDC1) and SLAMF7 were not or only moderately higher expressed in MM versus healthy plasma cells." (PMID 38942927, 2024). "Experiments with the bone marrow of non-myeloma patients demonstrated a tendency of greater CD38 (+) cell capture by AluSp and MER11C compared to controls or PC transposon sequences, with the trend disappearing in CD38 (–) cells." (PMID 38783375, 2024). "Notably, when combined with daratumumab (an anti-CD38 monoclonal antibody), iDuo-MM-CAR-NK cells achieved maximal ADCC activity and anti-tumor efficacy against multiple myeloma (MM)." (PMID 39682724, 2024). "During follow-up, Group A patients received significantly more subsequent, second line and beyond, multiple myeloma treatments (59.6%) than Group DVMP (22.8%); in total, 19 of them were treated with anti-CD38, 15 patients (48.4%) in Group A and 4 patients (30.8%) in Group B." (PMID 39458913, 2024). "Recently, a second revision of the International Staging System 2 (R2-ISS) was developed using 16 randomized clinical trial datasets by the European Myeloma Network, although clinical trials on CD38-MoAb-containing initial treatments were not included." (PMID 37173885, 2023). "CD38 is a NAD+-degrading enzyme that has become crucial for anti-MM therapies since anti-CD38 monoclonal antibodies represent the backbone for treatment of newly diagnosed and relapsed multiple myeloma patients." (PMID 36830052, 2023). "Proteasome inhibitors, immunomodulatory drugs, anti-CD38 monoclonal antibodies (triple class drugs), and autologous stem cell transplantation (ASCT) are promising myeloma treatments that have resulted in minimal residual disease (MRD) negativity and improvement in the bone marrow microenvironment." (PMID 37173885, 2023). "For example, CD33 and SLAF7, together with CD38 (which did not have plasma pQTL data), are targeted by mAbs for multiple myeloma." (PMID 37126556, 2023). "Although targeting CD38 antibodies has been approved for treatment of multiple myeloma, the role of CD38 in solid tumor, especially urothelial carcinoma, has not been investigated." (PMID 35725444, 2022).
multiple myeloma (continued). "CD38 is one of the targets in view of its high expression in several hematological malignancies, particularly in multiple myeloma (MM), with minimal or no expression in normal tissues." (PMID 36313735, 2022). "Consensus exists the utility of combined assessment of CD38 and CD138 for the identification of plasma cells, and CD38 emerged as a highly valuable PC-identification marker and can be reliably used for the identification of both normal and myeloma PCs." (PMID 35562760, 2022). "Validating our strategy, we identified nearly all known canonical diagnostic markers and immunotherapeutic targets in myeloma, including BCMA, CD138/SDC1, CD38, CD56, SLAMF7/CS-1, CD46, Integrin-b7 (ITGB7), CD74/HLA-DR, TACI, CD48/ SLAMF2, and LY9/CD229." (PMID 36311892, 2022). "Herein we present a rare case of CD38-negative multiple myeloma that was initially misdiagnosed as acute leukemia." (PMID 35004078, 2022). "Similarly, tumor cells from the myeloma PDX expressed both CD138 and CD38 and 70% of them were Ki-67+." (PMID 35992875, 2022). "These recruited CD16-expressing NK92 cells to exert potent cytotoxicity against CD38-expressing tumor cell lines in vitro and primary multiple myeloma cells ex vivo, independent of the epitope bound on CD38." (PMID 36405759, 2022). "The anti-CD38 antibody isatuximab is approved for the treatment of relapsed/refractory multiple myeloma, but there are no data on its efficacy in solid tumors." (PMID 35987165, 2022). "High expression of CD38 on the relevant cell surface in TIME induces an immunosuppressive microenvironment that inhibits effector T cell function and promotes tumor immune escape by promoting tumor angiogenesis, such as in multiple myeloma." (PMID 35906622, 2022). "Previous studies have shown that Tregs expressing CD39 inhibited the antitumor immunity mediated by NK cells and that anti-CD38 antibodies decreased Tregs’ suppression and restored CD4+CD25- T cell proliferation in multiple myeloma by decreasing the percentage of CD38 expression." (PMID 36268017, 2022). "Anti-CD38 treatment, which is used in multiple myeloma, was found to have a negative effect on the immune response." (PMID 35510135, 2022). "Prior treatment with anti-CD38 antibodies in multiple myeloma patients (14/30 patients) did not have any impact on seroconversion rates nor antibody titer levels." (PMID 36428605, 2022). "The major limitation of our proof-of-concept in vitro and ex vivo study is the lack of the assessment of cytotoxic effects of our CD38-specific HLE-nano-BiKEs in in vivo xenograft myeloma mouse models." (PMID 35651607, 2022). "With the exception of tumor burden, anti-BCMA CAR T-cell activity did not correlate with any other biological factor intrinsic to multiple myeloma primary cells, such as expression of CD38, CD138, CD56, or CD45." (PMID 36874402, 2022). "Our study demonstrates that a nanobody recognizing a distinct, non-overlapping epitope of CD38 allows the detection of myeloma cells pretreated with daratumumab." (PMID 36389758, 2022). "Two trials of combination therapy including the anti-CD38 monoclonal antibody daratumumab, set the new standard of care for non-transplant eligible newly diagnosed multiple myeloma (NDMM)." (PMID 35886976, 2022). "It is known that CD38 and CD138 are widely expressed on multiple myeloma cells." (PMID 35209102, 2022). "In addition to Fate's work with the FT538 and FT576 products, Indapta Therapeutics has shown that CD38-deficient g-NK cells can be preferentially expanded which could produce high efficacy in combination with daratumumab as an anti-myeloma product without resorting to genetic engineering." (PMID 35342342, 2022). "The results reveal that all three CD38-specific HLE-nano-BiKEs specifically induce the killing of CD38-expressing LP-1 myeloma cells, but not of CD38KO LP-1 myeloma cells." (PMID 35651607, 2022).
multiple myeloma (continued). "Our study demonstrates that a nanobody recognizing a distinct, non-overlapping epitope of CD38 allows the specific detection of myeloma cells under daratumumab therapy in vitro, ex vivo, and in vivo." (PMID 36389758, 2022). "Ruxolitinib upregulates CD38 expression via inhibition of STAT3 phosphorylation, thus enhances the DARA-mediated antibody-dependent cellular cytotoxicity (ADCC) against MM cell lines and primary CD138+ myeloma cells derived from MM patients." (PMID 35326392, 2022). "Two monoclonal antibodies directed at CD38, isatuximab and daratumumab, are available for use in patients with relapsed and/or refractory MM (RRMM); daratumumab is also approved in newly diagnosed MM and light-chain amyloidosis." (PMID 35943588, 2022). "Although the number of patients was small, this study is important because we tested and confirmed the efficacy of the anti-CD38 monoclonal antibody daratumumab in AL Amyloidosis without significant toxicity related to the drug in a real-life population." (PMID 35330483, 2022). "The highlight of ASH 2020 in therapeutic advances for multiple myeloma (MM) is undoubtedly BCMA-targeted immunotherapy, led by BITEs, CAR-T/NKs cells and ADC, followed by new CD38 monoclonal antibodies and the newer generation of immunomodulatory drugs (IMIDs)." (PMID 33879198, 2021). "Monoclonal antibodies targeting the plasma cell surface marker CD38, daratumumab and isatuximab, have revolutionized the standard of care treatment, and CAR T-cell therapy has been FDA-approved for the treatment of relapsed, refractory multiple myeloma." (PMID 34572773, 2021). "In multiple myeloma, novel antigens such as BCMA and CD38 are being explored for CAR T cells." (PMID 33466674, 2021). "Thus, anti CD38 and SLAMF-7 MoAbs can be active for myeloma cells in various differentiation stages." (PMID 33435539, 2021). "CD38 has been widely investigated in chronic lymphocytic leukemia (CLL) and multiple myeloma (MM)." (PMID 33467713, 2021). "Our group has previously showed that antibody-based PET nuclear agents, [89Zr]Zr-daratumumab and [89Zr]Zr-elotuzumab targeted to overexpressed proteins CD38 and CS1, respectively, on myeloma cells can be used as companion diagnostics for preclinical imaging of MM." (PMID 34586539, 2021). "While CD38 and SLAMF7 were detected at high levels on the surface of virtually all myeloma cells even in heavily pretreated patients, we found heterogeneous BCMA expression with substantial inter- and intra-individual differences and the regular occurrence of BCMA-negative subpopulations." (PMID 33420283, 2021). "Patients receiving anti-myeloma treatment without any anti-CD38 regimens were more likely to respond to vaccination." (PMID 34341335, 2021). "We did not observe correlation between myeloma patient sample CD138+CD38+ cell melflufen sensitivity and aminopeptidase gene expression in a small set of 10 myeloma samples." (PMID 33810334, 2021). "CD38 research originally focused on hematological tumors, including CLL and multiple myeloma." (PMID 34211854, 2021). "At the time of treatment failure and development of progressive disease, there is no further reduction of the expression of CD38 by myeloma cells." (PMID 32041300, 2020). "In the study NCT03464916, a CD38 CAR T-cell product is being used as monotherapy for relapsed/refractory myeloma to evaluate its efficacy and safety although no outcomes have been posted yet." (PMID 32582204, 2020). "In recent years, the introduction of monoclonal antibodies (mAbs) targeting CD38 and the signaling lymphocytic activation molecule family member 7 (SLAMF7) represents an important step towards the treatment of relapsed/refractory multiple myeloma (RRMM) patients." (PMID 32899714, 2020). "Few RIT studies have evaluated this target potency, and none have evaluated 212Pb-anti-CD38 RIT in myeloma." (PMID 31862796, 2020).